NICOL1 (NELL2 interacting cell ontogeny regulator 1)
Description:
mRNA-binding protein which interacts with a range of target mRNAs including SERPINE1, ACTA2, CCN2 and COL4A1 and may promote extracellular matrix production. Binds to the 3'-UTR of SERPINE1 mRNA and stabilizes the mRNA, possibly by competing for binding with SERBP1 and preventing SERBP1-mediated mRNA degradation. Also binds to the 3'-UTR of ACTA2. Testis-derived lumicrine factor that triggers epididymal differentiation and sperm maturation.
Synonyms: NICOL; C4orf48; CHR4_55
Tractability: Antibody: UniProt places it where antibodies can reach, with medium confidence; UniProt predicts a signal peptide or a membrane-spanning region; its Gene Ontology location is reachable by antibodies, with medium confidence.
Gene: Protein-coding gene on chromosome 4 (2,040,628 to 2,043,964, forward strand). Ensembl gene ENSG00000243449.
Subcellular location: Secreted; Cytoplasm, perinuclear region
Subcellular location (Human Protein Atlas): Cytosol; Predicted to be secreted
Gene Ontology:
Molecular function: mRNA 3'-UTR binding
Biological process: 3'-UTR-mediated mRNA stabilization; spermatogenesis
Cellular component: extracellular region; perinuclear region of cytoplasm
Genetic constraint (gnomAD): Loss-of-function variants: 5 observed, 4.77 expected, observed/expected ratio (o/e) 1.05, 90% interval 0.54 to 1.83. That is too few expected variants to judge how well the gene tolerates losing a copy. Missense variants: 70 observed, 61.22 expected, observed/expected ratio (o/e) 1.14, 90% interval 0.94 to 1.39. Synonymous variants: 37 observed, 26.72 expected, observed/expected ratio (o/e) 1.38, 90% interval 1.06 to 1.8.
Homologues: Orthologues: chimpanzee NICOL1 (98% identical), macaque NICOL1 (98% identical), dog NICOL1 (85% identical), pig NICOL1 (84% identical), mouse Nicol1 (82% identical), guinea pig NICOL1 (79% identical), rat Nicol1 (79% identical), zebrafish nicol1 (45% identical), tropical clawed frog NICOL1 (44% identical).
Diseases named in the same sentence as NICOL1 in open-access papers:
NICOL1 is named in the same sentence as 13 diseases in open-access papers, as found by Europe PMC text mining. Sharing a sentence is not in itself a finding about the gene and the disease. The quoted sentences say what the papers report.
renal fibrosis (2 papers, 2024 to 2025). A final common manifestation of a wide variety of chronic kidney diseases characterized by glomerulosclerosis and tubulointerstitial fibrosis. "NICOL1 has also been shown to enhance renal fibrosis in mice by interacting with and stabilising mRNAs of profibrotic molecules, an effect which was reversed upon Nicol1 ablation in mice." (PMID 39747179, 2025). "The present study used ribosome profiling and bioinformatics analysis to screen a mouse diabetic kidney disease and identified secreted micropeptide C4orf48 (Cf48 for brevity, also known as NICOL1) as a candidate molecule involved in renal fibrosis." (PMID 38625739, 2024).
fine-motor disabilities (1 paper, 2025). "Based on its expression in developing and adult cortical and subcortical mouse neurons, Nicol1 has been suggested to have a role in the etiology of intellectual and fine-motor disabilities." (PMID 39747179, 2025).
NICOL1 also shares sentences with these, for which no sentence is quoted: microcephaly (3 papers); cancer (2); tumor (2); atherosclerosis (1); convulsion (1); diabetic kidney disease (1); Intellectual disability (1); male infertility (1); metastatic tumor (1); periodontitis (1); prostate carcinoma (1).